UPRT (uracil phosphoribosyltransferase homolog)
Synonyms: DKFZp781E1243; MGC23937; FUR1; RP11-311P8.3; UPP
Tractability: PROTAC: ubiquitination databases record sites on it; its protein half-life has been measured.
Gene: Protein-coding gene on chromosome X (75,156,388 to 75,304,885, forward strand). Ensembl gene ENSG00000094841.
Subcellular location: Cytoplasm; Nucleus
Subcellular location (Human Protein Atlas): Nucleoplasm; Vesicles
Gene Ontology:
Molecular function: protein binding; nicotinate riboside kinase activity; ribosylnicotinamide kinase activity
Biological process: female pregnancy; lactation; response to insulin; UMP biosynthetic process
Cellular component: nucleoplasm; cytoplasm; nucleus
Homologues: Orthologues: macaque UPRT (97% identical), chimpanzee UPRT (89% identical), guinea pig UPRT (88% identical), pig UPRT (87% identical), mouse Uprt (86% identical), rabbit UPRT (86% identical), rat Uprt (85% identical), dog UPRT (85% identical), zebrafish uprt (65% identical), tropical clawed frog uprt (65% identical), Drosophila melanogaster kri (48% identical), Caenorhabditis elegans C47B2.2 (37% identical). Paralogues in human: UCKL1 (34% identical), UCK1 (8% identical), UCK2 (8% identical).
Diseases named in the same sentence as UPRT in open-access papers:
UPRT is named in the same sentence as 12 diseases in open-access papers, as found by Europe PMC text mining. Sharing a sentence is not in itself a finding about the gene and the disease. The quoted sentences say what the papers report.
glioblastoma (2 papers, 2021 to 2022). The most malignant astrocytic tumor (WHO grade IV). "In addition, an in vivo study using genetically engineered EVs carrying the suicide gene for cytosine deaminase (CD) fused to uracil phosphoribosyltransferase (UPRT) demonstrated a reduction in the tumor growth in the glioblastoma mice model after treatment with the CD-UPRT-enriched EVs." (PMID 35422699, 2022).
nerve sheath tumor (2 papers, 2016 to 2020). "For example, the fusion protein of cytosine deaminase (CD) and uracil phosphoribosyltransferase (UPRT) has been successfully expressed on transfected 293T cell-derived microvesicles, which synergized with chemo prodrug 5-fluorocytosine to induce nerve sheath tumor apoptosis and regression." (PMID 32375399, 2020).
breast carcinoma (1 paper, 2023). "Moreover, the current study found that the overexpression of UPRT was associated with a worse prognosis in breast cancer and is closely related to cancer gene-therapy efficacy." (PMID 36960071, 2023). "This study developed a signature featuring 8 OARGs (HLA-B, RBBP8, SPRY4, WT1, WWOX, UPRT, PELO, ZNF208) and determined its prognostic and functional implications in breast cancer patients." (PMID 36960071, 2023).
cyst (1 paper, 2022). A sac-like closed membranous structure that may be empty or contain fluid or amorphous material. "It should be noted that disruption of the UPRT locus has been documented to negatively affect cyst burden, which would suggest that our data might underrepresent barcode diversity in the CNS." (PMID 36046624, 2022).
lung carcinoma (1 paper, 2021). "This study confirmed that suicide gene therapy by expressing UPRT gene under the control of STC‐1 promoter was effective to target STC‐1‐expressing lung cancer cells." (PMID 33826244, 2021). "A vector in which the suicide gene uracil phosphoribosyltransferase (UPRT), internal ribosome entry site (IRES), and EGFP gene were ligated downstream of the PSTC‐1–114 was constructed and transfected into STC‐1‐expressing lung cancer cell lines PC‐9, A549, and H1299." (PMID 33826244, 2021).
schwannoma (1 paper, 2023). A benign, usually encapsulated slow growing tumor composed of Schwann cells. "In another study regarding Schwannoma treatment, exosomes containing CD-UPRT mRNA were released after donor cells were transfected with a plasmid encoding a cytosine deaminase (CD) fused with uracil phosphoribosyltransferase (UPRT)." (PMID 36839920, 2023).
tumor (7 papers, 2014 to 2024). "To translate this strategy to clinical application, we are generating adenovirus vectors to deliver hypoxia-regulated TK, CD and UPRT genes into in vivo tumor models and to test whether triple gene transduction following GCV and 5-FC treatment will improve the efficacy of radiotherapy." (PMID 24912473, 2014). "Several studies provide compelling evidence that MSCs can be genetically engineered to deliver anti-tumor drugs (PTX, DOX) and immunomodulatory factors (IL-12, IL-24, IFN-Υ, IFN-β, TRAIL, PEDF, apotin, CDA/UPRT and CX3CL1) to target cells, thereby conferring anti-tumor/anti-metastatic actions." (PMID 36739406, 2023). "The UPRT gene was detected in tumor tissues of PSTC‐1‐UPRT‐PC‐9 but not of PSTC‐1‐Null‐PC‐9." (PMID 33826244, 2021).
UPRT also shares sentences with these, for which no sentence is quoted: cancer (3 papers); acute myeloid leukemia (1); infection (1); malignant brain tumor (1); pancreatic cancer (1).